TMEM183BP (transmembrane protein 183B, pseudogene)
Synonyms: C1orf37-dup; TMEM183B; C1ORF37DUP
Gene: Processed pseudogene on chromosome 3 (149,982,181 to 149,983,308, reverse strand). Ensembl gene ENSG00000224831.
Subcellular location: Membrane